SMAD4 (SMAD family member 4)
Diseases named in the same sentence as SMAD4 in open-access papers (continued):
Sharing a sentence is not in itself a finding about the gene and the disease.
acute myeloid leukemia (6 papers, 2010 to 2024). Acute myeloid leukemia (AML) is a group of neoplasms arising from precursor cells committed to the myeloid cell-line differentiation. "Furthermore, mutations in Smad4 can block nuclear translocation of this gene, which is associated with the pathogenesis of acute myelogenous leukemia." (PMID 25161335, 2014). "For example, in acute myeloid leukemia (AML), two distinct mutations in Smad4 (a missense mutation and a frameshift mutation) disrupt its ability to potentiate TGF-β transcriptional activity." (PMID 28052022, 2017).
autoimmune disease (6 papers, 2017 to 2023). A disorder resulting from loss of function or tissue destruction of an organ or multiple organs, arising from humoral or cellular immune responses of the individual to their own tissue constituents. "A later study found that co-Smad4 depletion rescued lethal autoimmune disease in T-cell-specific TGFβRΙΙ-deficient mice, suggesting that co-Smad4 counterbalances TGFβR signaling." (PMID 37217798, 2023). "Because impaired Treg cells are linked to the development of autoimmune disease, we investigate the function of Treg cells from Smad4 tKO and WT NOD mice by examining their ability to inhibit the proliferation of Teff cells." (PMID 27686408, 2017).
gastric adenocarcinoma (6 papers, 2015 to 2024). "In gastric adenocarcinoma with enteroblastic differentiation, an inactive SMAD4 is associated with a worse clinical outcome." (PMID 39039246, 2024). "As a transcription factor of Smad4, MZF1 directly binds to the core region of the Smad4 promoter, stimulates transcriptional activity, upregulates the expression of Smad4, and then inhibits the migration ability of gastric adenocarcinoma cells." (PMID 37654657, 2023). "The methylation of TGF-β RI, TGF-β RII, and Smad4 has been observed during the early stages of gastric adenocarcinoma." (PMID 26583078, 2015). "In one study, the expression of the common SMAD mediator Smad4 and the inhibitory SMAD protein Smad7 was examined in gastric adenocarcinomas." (PMID 26583078, 2015).
glioblastoma (6 papers, 2013 to 2020). The most malignant astrocytic tumor (WHO grade IV). "Supporting this idea, an interaction of SNAIL1 with SMAD1 and SMAD4 was recently shown in glioblastoma." (PMID 32326239, 2020). "This was further supported by an analysis of the data in The Cancer Genome Atlas which revealed an upregulated SMAD4 level in glioblastoma tumors as compared to normal brain samples." (PMID 29861845, 2018). "In the present study, double immunofluorescence analysis was performed to determine SMAD4 protein expression in glioblastoma tissues." (PMID 29861845, 2018). "In our model, SMAD4 resulted to be the best candidate target at transcriptional level, in line with regulation of SMAD4 by miR-34a that has been recently shown in glioblastoma." (PMID 26123714, 2015). "This protein has been found to have an oncogenic role in sarcomas and in glioblastoma, while SMAD4 silencing induced growth inhibition and apoptosis in rhabdomyosarcoma cells." (PMID 26123714, 2015). "Immunofluorescence labeling further revealed the expression of SMAD4 in microglial and non-microglial cells of human glioblastomas tissue in vivo." (PMID 29861845, 2018).
intestinal cancer (6 papers, 2017 to 2025). "SMAD4 patients harbour a high risk of early-onset bowel cancer (25% at a median age of 33 years), which proved fatal in almost half of patients." (PMID 38627541, 2024). "Smad4 haploinsufficiency reportedly affects mouse intestinal tumorigenesis and progression and Smad4 deletion in combination with genetic alterations in antigen‐presenting cell (APC) results in intestinal cancer in mice." (PMID 35274815, 2022). "Smad4 deletion along with an APC alteration results in intestinal cancer in mice." (PMID 35274815, 2022).
intestinal polyposis (6 papers, 2022 to 2025). "This also indicates that SMAD4 and BMPR1A should be included in the panel of genes analyzed in all patients suspected to suffer from a genetic predisposition to intestinal polyposis." (PMID 37354305, 2023). "This matches the previous reports on Smad4 as a model for intestinal polyposis." (PMID 38891999, 2024).
intestinal tumors (6 papers, 2007 to 2023). "Invasive intestinal tumors of cis-Apc+/716;Smad4+/+ mice that exhibited bi-allelic loss of heterozygosity were observed to have marked increased expression of CCL9 and resultant accumulation of immature myeloid cells compared to tumors arising from Apc+/716;Smad4+/+ controls." (PMID 33834163, 2019). "Additionally, mouse and human Smad4/SMAD4-deficient intestinal tumors have been associated with increased immune cell accumulation compared to SMAD4-expressing controls." (PMID 33834163, 2019). "Of note, the abundance of TGF‐β1 was also increased in intestinal tumors from Smad4−/− mice treated with AOM/DSS." (PMID 37261975, 2023). "Similarly, YAP and TGF‐β1 were concurrently elevated in the AOM/DSS‐induced Smad4−/− intestinal tumors." (PMID 37261975, 2023). "Moreover, combined activation of canonical WNT signaling and inhibition of TGFβ signaling also results in more advanced intestinal tumors in Apcdelta716/+; Smad4+/- mice, and intestine-specific deletion of the type II TGFβ receptor in Apc1638N/wt mice." (PMID 17615082, 2007).
intrahepatic cholangiocarcinoma (6 papers, 2019 to 2025). A carcinoma that arises from the intrahepatic bile duct epithelium in any site of the intrahepatic biliary tree. "Interestingly, Smad4 was found to be overexpressed in most extrahepatic cholangiocarcinoma patients, whereas the inactivation of Smad4 was identified in intrahepatic cholangiocarcinoma, which might be due to tumor heterogeneity." (PMID 31349837, 2019).
keloid (6 papers, 2013 to 2023). An irregularly shaped, elevated mark on the skin caused by deposits of excessive amounts of collagen during wound healing. "We clarified a novel mechanism of positive regulation of sumoylation in keloids and demonstrated the function of sumoylation in Smad4 nuclear export." (PMID 36916534, 2023). "Jialiang el al., which was the first study to demonstrate increased Smad4 expression and decreased Smad7 expression in keloids, proposed that Toll-like receptors (TLRs) exert contribute to keloidogenesis through TGF-β/Smad signaling." (PMID 33931723, 2021). "Hypoxia up-regulated TGF-β1, Smad2/3, p-Smad2/3, Smad4, and total collagen in both normal and keloid fibroblasts via HIF-1α, which was attenuated by HIF-1α inhibition, but TβRII levels were not significantly altered." (PMID 29423039, 2018). "Previously studies demonstrate that phosphatase and tensin homolog (PTEN), insulin-like growth factor I receptor (IGF-IR) and SMAD4 are substrates of NEDD4, which have been reported to be associated with keloid." (PMID 23667473, 2013).
lung squamous cell carcinoma (6 papers, 2017 to 2026). "For lung tumors, TCGA data demonstrate heterozygous Smad4 loss in 13% of lung squamous cell carcinomas and 47% of lung adenocarcinomas." (PMID 34381046, 2021).
rectal tumors (6 papers, 2016 to 2025). "CYT-high rectal tumors on the other hand, had recurrent deletions at loci 3p21.31 (RHOA), 5q22.2 (APC), 10q26.2 (MGMT), 14q32.2 (AKT1, EIF5, YY1), 18q21.2 (SMAD4, MAPK4), and a single amplification in 7p15.3 (STK31)." (PMID 31429779, 2019). "For example, although at low frequencies, we found that the PTEN gene was deleted, with a gradually increasing frequency from ascending tumors to the rectum, while both the deletion of SMAD4 and amplification of ERBB4 were enriched in descending or rectal tumors (P < 0.05)." (PMID 35487942, 2022).
aneurysm (5 papers, 2015 to 2024). Bulging or ballooning in an area of an artery secondary to arterial wall weakening. "Apart from SMAD3, the relationship between SMAD4 and aneurysms also has been studied." (PMID 34093163, 2021). "Indeed the underlying molecular mechanisms of the intricate interplay of TGF-β, SMAD2, SMAD3 and SMAD4 in the pathogenesis of aneurysm remains to be determined." (PMID 25985281, 2015).
aortic aneurysm (5 papers, 2020 to 2024). A ruptured aneurysm located in the wall of the proximal portion of the descending aorta proceeding from the arch of the aorta. "Though no direct relationship has been established between fluoroquinolones and SMAD4 pathogenic variants, both are associated with an increased risk for aortic aneurysms and dissections." (PMID 35685436, 2022). "Patients harboring SMAD4 variants are known to possess an increased risk for collagen-associated disorders, including aortic aneurysm or aortic dissection." (PMID 35685436, 2022). "Loss-of-function mutations or deficiency of SMAD2, SMAD3, and SMAD4 genes in mice or humans lead to the formation of aortic aneurysms or dissections, suggesting that basal TGF-βsignaling canonical signaling is indispensable for maintaining the integrity of aortic structure and function." (PMID 35517795, 2022). "In addition, they demonstrated that Smad4 deficiency in SMCs directly triggers an inflammation-mediated progression of aortic aneurysms." (PMID 33110393, 2020). "The Smad4-haploinsufficient MFS mouse model (Smad4+/−: Fbn1C1039G/+ genotype) showed a larger aortic aneurysm and higher mortality rate than the MFS mouse model." (PMID 34769168, 2021). "Therefore, the upregulation of the Smad4-dependent TGF-β signaling pathway in SMCs protected against aortic aneurysm formation and dissection." (PMID 34769168, 2021).
breast ductal carcinoma (5 papers, 2006 to 2023). "Furthermore, even though functional characterization of the role of Snail-Smad3/4 on the CAR promoter was conducted in mouse cells, in invasive human ductal breast carcinoma, nuclear expression of Snail, Smad3 and Smad4 correlated with loss of CAR expression at the invasive front." (PMID 21791114, 2011). "Smad4 expression was found to be reduced in lobular and ductal breast carcinoma as compared to surrounding uninvolved lobular and ductal breast epithelia (p < 0.001, n = 50)." (PMID 16438724, 2006). "Another recently published paper showed that Smad4 mRNA expression is reduced in ductal carcinoma as compared to normal tissues." (PMID 16438724, 2006).
colorectal adenoma (5 papers, 2008 to 2023). An adenoma that arises from the colon or rectum. "Thus, we analyzed transcriptional responses to TGFβ in Smad4-deficient and Smad4-reexpressing SW480 cells as well as in Smad4-positive LT97 colorectal adenoma cells." (PMID 18664273, 2008). "Next, the activities of the promoter-reporter constructs were tested in Smad4-negative and Smad4-positive clones of the SW480 and BxPC3 cell lines as well as in the Smad4-positive colorectal adenoma cell line LT97 in the absence and in the presence of TGFβ." (PMID 18664273, 2008).
Crohn disease (5 papers, 2018 to 2025). A gastrointestinal disorder characterized by chronic inflammation involving all layers of the intestinal wall, noncaseating granulomas affecting the intestinal wall and regional lymph nodes, and transmural fibrosis. "Accordingly, CD103 blockade alleviates intestinal immunopathology in both SMAD4-deficient mice and human patients with Crohn’s disease, pinpointing the central role of gut epithelial retention of CD8+ T cells in IBD development." (PMID 35426367, 2022). "Based on the entire cohort, SMAD4 mutations were significantly more prevalent among patients with Crohn’s disease than others (4/7 [57%] vs. 24/436 [5.5%], P = 0.0041; 3/5 [60%] vs. 24/436 [5.5%], P<0.0001 for CRCs only)." (PMID 30730996, 2019). "•TINAGL1-SMAD4 Interaction: We demonstrate a significant interaction between TINAGL1 and the transcription factor SMAD4, highlighting a previously unexplored pathway in fibrogenesis, with implications for the exacerbation of Crohn's Disease." (PMID 38750695, 2025). "Nevertheless, the potential role of SMAD4 function in Crohn’s disease was demonstrated in a recent study showing downregulation of the SMAD4 protein in ileal epithelial cells of patients with Crohn’s disease." (PMID 30730996, 2019). "Prior studies of ACA complicating Crohn’s disease either did not report or did not observe increased proportions of SMAD4 mutations compared to sporadic ACAs." (PMID 30730996, 2019). "We found a significantly high percentage of SMAD4 mutations in ACAs from patients with Crohn’s disease, with or without inclusion of small intestine ACAs, warranting future larger studies to validate and further explore this association." (PMID 30730996, 2019).
diabetic nephropathy (5 papers, 2019 to 2024). "A mitochondrial role of SMAD4 in the pathogenesis of diabetic nephropathy has been reported recently." (PMID 36290802, 2022). "As part of the TGF-β1 pathway, SMAD proteins, particularly SMAD2, SMAD3, SMAD4, and SMAD7, are crucial in diabetic nephropathy." (PMID 38972889, 2024). "Strikingly, the protein levels of TGF-β1, phosphor-Smad2, Smad4, and Smad7 were reversed after 8-weeks treatment with ergosterol, indicating that ergosterol can inhibit the renal TGF-β1/Smad2 signaling pathway in STZ-induced diabetic nephropathy mice." (PMID 30823598, 2019).
esophageal adenocarcinoma (5 papers, 2015 to 2023). A malignant tumor with glandular differentiation arising predominantly from Barrett mucosa in the lower third of the esophagus. "Abnormalities within the Sonic Hedgehog (SHH), Bone Morphogenetic Protein (BMP) and SMAD4 signalling pathways have been associated with the malignant behavior of esophageal adenocarcinoma (EAC)." (PMID 35902550, 2022). "It has been shown that loss of members of the TGFβ signaling cascade, such as Smad4 and β2 spectrin, can contribute to the initiation of Barrett's esophagus and the progression to esophageal adenocarcinoma through concomitant upregulation of Notch targets Hes1 and Jagged1." (PMID 26447543, 2015). "For SMAD4, about 70% of esophageal adenocarcinoma (EAC) associated with Barrett’s esophagus (BE) revealed loss of heterozygosity in a region involving SMAD2 and SMAD4 on chromosome 18q." (PMID 37892233, 2023). "However, loss of heterozygosity of the SMAD4 and APC loci shows a heterogeneous pattern, indicating intratumor heterogeneity of esophageal adenocarcinoma." (PMID 28376920, 2017). "The disruption of TGFβ/Smad-dependent signaling during the progression of esophageal adenocarcinoma was confirmed by a report that showed Smad4 mRNA expression was progressively reduced in the metaplasia-dysplasia-adenocarcinoma sequence by promoter methylation." (PMID 26447543, 2015).
Fanconi anemia (5 papers, 2016 to 2023). Fanconi anemia (FA) is a hereditary DNA repair disorder characterized by progressive pancytopenia with bone marrow failure, variable congenital malformations and predisposition to develop hematological or solid tumors. "However, SMAD4 expression is known to be associated with other activated SMAD proteins linked to the Fanconi anemia/BRCA DNA repair pathway." (PMID 28256094, 2017). "These genes include DDIT3 (DNA damage-inducible transcript 3), FANCM (Fanconi anemia, complementation group M), Merlin tumor suppressor, NME1 (NME/NM23 nucleoside diphosphate kinase 1), SMAD4." (PMID 37239070, 2023).
inflammatory bowel disease (5 papers, 2021 to 2025). A spectrum of small and large bowel inflammatory diseases of unknown etiology. "Besides, the downexpression of SMAD4 is strongly associated with intestinal tumorigenesis in mice with inflammatory bowel disease, with the abnormal proliferation of intestinal epithelium." (PMID 34692671, 2021). "SMAD4, a mediator of TGF-β signaling, plays an important role in T cells to prevent inflammatory bowel disease (IBD)." (PMID 35426367, 2022).
intestinal polyp (5 papers, 2009 to 2024). Discrete abnormal tissue masses that protrude into the lumen of the intestine. "IHC clearly showed SMAD4 loss of expression in the epithelial cells of both the gastric and intestinal polyps, whereas inflammatory and stromal cells showed a retained expression of the protein in the nuclei." (PMID 35075588, 2022). "Cases with SMAD4 variants usually feature both gastric and intestinal polyps, and a large fraction displays high-grade adenomatous lesions and malformative vessels, while cases with BMPR1A variants feature only colorectal polyps with lack of adenomatous aspects and malformative vessels." (PMID 35075588, 2022). "Moreover, the vast majority of the Apc+/1572T/Smad4+/Sad intestinal polyps show loss of the entire chr." (PMID 19578404, 2009).
lymphoma (5 papers, 2012 to 2023). A malignant (clonal) proliferation of B- lymphocytes or T- lymphocytes which involves the lymph nodes, bone marrow and/or extranodal sites. "Both T-linkage and B-linkage lymphoma have been associated with SMAD4 or related pathways, implying the specific role of SMAD4 during the initiation and progression of lymphoma." (PMID 34899868, 2021). "With respect to MLH1−/− tumors, SMAD4 mutations were constrained to lymphomas." (PMID 31581674, 2019). "Consistent with these previous findings, we found that combination treatment decreased Smad3 phosphorylation and reduce nuclear accumulation of Smad4 in lymphoma cells in vitro and in vivo." (PMID 34324434, 2021). "All lymphoma cell lines in this study expressed Smad4 although at different levels, and SMAD4 mRNA had similar expression levels across different NHLs." (PMID 23049692, 2012). "Although the protein level of Smad4 varied between lymphoma cell lines, it did not correlate with sensitivity to BMPs." (PMID 23049692, 2012).